AFP (alpha fetoprotein)
Diseases named in the same sentence as AFP in open-access papers (continued):
Sharing a sentence is not in itself a finding about the gene and the disease.
tumor (continued). "On the other hand, low SOD2, higher Serum AFP, tumor embolus, multiple tumors, advanced TNM, BCLC, and postoperative metastasis were statistically significantly correlated with shorter RFS in HCC patients." (PMID 27221200, 2016). "In the present study, factors that resulted in poor long-term outcomes after hepatic resection were identified, including preoperative AFP level, macroscopic vascular invasion, the largest tumor size >5 cm, multiple tumor nodules, and microscopic portal vein." (PMID 26936459, 2016). "Our univariate analysis showed that age, preoperative Child-Pugh score, preoperative AFP value, preoperative hepatitis B virus DNA, tumor size, microvascular invasion, and satellite nodules were associated with postoperative recurrence." (PMID 27038790, 2016). "Tumor response: favor TCM.Quality of life: favor TCM.Immunolisation: favor TCM.Recovery of liver function: favor TCM.AFP concentration: lower in TCM.Reduction in chemotherapy toxicities: favor TCM." (PMID 27167195, 2016). "We compared iHCC and pdHCC groups regarding tumor characteristics and found that patients in the former group had lower alpha-fetoprotein levels, smaller tumor diameters, and smaller total tumor volume as expected." (PMID 27403337, 2016). "Univariate analysis showed that age, Child-Pugh score, preoperative AFP values, hepatitis B virus DNA levels, tumor size, microvascular infiltration, and satellite nodules were significantly related to recurrence (P < 0.05)." (PMID 27038790, 2016). "As surrogate parameters that reflect the tumor biology, response to local ablative therapies, serum alpha fetoprotein concentration and the tumor-free interval between treatment and LT can be used." (PMID 27590261, 2016). "In a previous relatively small-sized study, we have identified that age >60 years, tumor size >5cm, α-fetoprotein (AFP) level >1000ng/ml and HBV viral load >2,000 IU/mL after tumor resection, to be associated with increased cumulative risk of HCC recurrence." (PMID 26901762, 2016). "Univariate analyses showed that tumor size, AFP, number of TACE procedures, BCLC stage, and the degree of lipiodol deposition after the 1st TACE procedure were significantly associated with OS (p < 0.05)." (PMID 26769845, 2016). "Presurgery tumour markers, retrospectively analysed serum samples, revealed an alpha-fetoprotein (AFP) of 22854 ng/mL, human chorionic gonadotropin (HCG) of <1 mIU/mL, and LDH of 473 IU/L (10–250 IU/L)." (PMID 27830100, 2016). "Many biomarkers, such as AFP in serum, tumor differentiation, BCLC classification, and MVI, have previously been identified as independent risk factors in HCC progression." (PMID 27542259, 2016). "Elevated preoperative serum γ-GGT was significantly associated with high alpha-fetoprotein (AFP), large tumor size, and macro- and micro-vascular invasion." (PMID 27381639, 2016). "In total, 755 DEGs (747 mRNA and eight lncRNA) were identified, and several co-expression modules were significantly associated with HCC clinical traits, including tumor location, tumor grade, and the α-fetoprotein (AFP) level." (PMID 27220887, 2016). "During this differentiation, an EC-intermediate step is skipped (no upregulation of SOX2) and a strong upregulation of germ layer differentiation markers, like AFP (also a yolk-sac tumor marker) and HAND1 was observed." (PMID 27283990, 2016). "To validate the established PDX models, we compared their morphology, immunological markers (GPC3 and AFP), and gene expressions with those of the corresponding primary tumor." (PMID 28123387, 2016). "In univariate analyses of our data, AFP, HBsAg, platelet counts, tumor multiplicity, tumor differentiation, tumor size, vascular invasion, TNM stage, and BCLC stage were prognostic indicators of OS and/or RFS." (PMID 27129159, 2016).
tumor (continued). "From clinical records we ascertained the contribution of AFP to HCC diagnosis for 129 patients undergoing HCC surveillance (excluding the four incidental tumours found at liver transplant explant analysis)." (PMID 27308823, 2016). "Isolated splenocytes from mice were stimulated in vitro with the AFP peptide followed by analysis of viable effector cells for cytotoxic activity against Hepa1-6 or H22 tumor cells." (PMID 27713135, 2016). "The re-expression of AFP occurs in 50 to 80% of HCC patients during tumor progression, and the serum AFP levels play an important role in HCC diagnosis and the monitoring of responses to treatment." (PMID 27220887, 2016). "They found that the high expression of ALDH1A1 was significantly relative to low serum levels of AFP, small tumor diameter, very little lymphovascular invasion, more differentiated pathology, and good stage." (PMID 27610139, 2016). "Reduction of CD90 and AFP in the tumor tissue of MB109 group was also observed by immunohistochemistry analysis (respectively)." (PMID 27650540, 2016). "Serum MDK was also superior to AFP in the diagnosis of NASH-HCC and was associated with more aggressive tumour clinicopathological features." (PMID 27219517, 2016). "All iHCC cases were within the TTV/AFP criteria utilized in our center since 2007, which are based on total tumor volume of <115 cc3 and alpha-fetoprotein of <400 ng/mL." (PMID 27403337, 2016). "THA was referred to a hepatology clinic when recent laboratory studies revealed a slowly increasing tumor marker—alpha-fetoprotein level (AFP)." (PMID 29670812, 2016). "There were no statistical correlation between MEK1/SIRT1 expression and some clinicopathological parameters, such as patient age, gender, AFP level in serum, tumor interstitial hyperplasia, necrosis and recurrence." (PMID 26967560, 2016). "His baseline tumour markers showed alpha fetoprotein (AFP) level of 36920 ng/mL [normal value: <5 ng/mL] and lactate dehydrogenase (LDH) level of 893 iu/L [normal value: 140–333 iu/L]." (PMID 27807495, 2016). "Further, multivariate analysis showed that only HBV, AFP, tumor size, vascular invasion, and additional surgery were independent risk factors for RFS." (PMID 27495026, 2016). "CPS and ECOG PST (composing the ITA.LI.CA functional score) and AFP level are well known variables used to evaluate treatment feasibility and aggressiveness within each tumor stage." (PMID 27116206, 2016). "The other study analyzed 57 patients and showed correlation between AFP levels and the size of the recurrent tumor." (PMID 27304617, 2016). "Increased AFP level and advanced T category have long been regarded as indicators of tumor burden as well as the aggressive behavior of the HCC." (PMID 27880930, 2016). "The results showed that CTSB expression, serum AFP, tumor size, tumor recurrence and stage were recognized as independent prognostic factors of survival." (PMID 26896959, 2016). "On multivariate analysis, independent significant prognosticators of OS were: tumor number, tumor size, AFP, GGT and types of recurrence." (PMID 27620527, 2016). "Recently, studies have shown that AFP plays a critical role in HCC cells resistance to anti-tumour drug effects and AFP expression was positively associated with HCC recurrence and metastasis." (PMID 27716619, 2016). "Previous studies have found that circulating CCCK-18 levels were associated with the presence of metastasis, serum levels of AFP and tumor size." (PMID 27618033, 2016). "Univariate analysis identified AFP, tumor size, Edmondson–Steiner stage, surgical margin, PVTT, vascular invasion, GPR, blood loss, and blood transfusion as elements that have strong association with the DFS after patients’ hepatectomy." (PMID 27399101, 2016). "As for OS, univariate analyses identified 5 significant prognosticators: tumor size, levels of AFP and GGT, technique effectiveness and types of recurrence." (PMID 27620527, 2016).
tumor (continued). "A study implied that DLK1 was an independent prognostic factor that the expression of it did not seem to correlate with other classic prognostic factors such as AFP, tumor-node-metastasis (TNM), and vascular invasion." (PMID 27610139, 2016). "These include recombinant plasmid DNA, chimeric virus-like particles, viral or bacterial vectors expressing AFP proteins and adoptive transfer of tumor-specific T cells." (PMID 27713135, 2016). "Preoperative serum γ-GGT increased with AFP > 400 ng/ml (P = 0.002), larger tumor (P < 0.001), and macro- (P < 0.001) and micro-vascular invasion (P = 0.001)." (PMID 27381639, 2016). "The study also found that TNM stage, AFP and tumor differentiation degree, male, positive HBsAg, and FOXO6 were independent risk factors affecting HCC prognosis." (PMID 27227932, 2016). "There was a significant difference in performance status (PS), portal vein (PV) invasion, age, tumor size, and α-fetoprotein (AFP) levels between the 2 groups." (PMID 27486881, 2016). "In this study, we performed CEUS with Sonazoid and measured well‐known tumor markers, including serum AFP, AFP‐L3, and DCP, before RFA." (PMID 27748052, 2016). "The typical preoperative laboratory examination (blood routine and coagulation profile) and the values of the specific tumor markers AFP, LDH, CEA, and b-HCG were normal." (PMID 28003830, 2016). "Tumour rupture and an AFP > 10,000 are absolute contraindications as are extrahepatic spread and macroscopic vascular invasion." (PMID 27413539, 2016). "Comparison of AFP levels at baseline and at 4–8 weeks following first-line treatment, based on treatment type and tumor response." (PMID 27304617, 2016). "Subsequently, we analyzed the association of various combinations of T/N and AFP stages with prognosis to understand the interaction of primary tumor and lymph nodes with AFP status." (PMID 27835609, 2016). "Tumor markers, such as α-fetoprotein (AFP), are relatively insensitive surveillance tools for the detection of chronic liver disease." (PMID 26886558, 2016). "Other laboratory tests including full blood count, liver function test, troponin, electrolytes and glucose were normal as were the tumor markers beta human chorionic gonadotrophin (hCG) and alpha-fetoprotein." (PMID 26842759, 2016). "The univariate analysis showed that the size of the primary HCC, serum AFP level, tumor number, total radiation dose, radiotherapeutic response of PVTT, and additional locoregional therapy were significant factors." (PMID 27999803, 2016). "Combined with assessment of tumor markers such as AFP, B-mode US has been a well-established surveillance tool for patients at risk of HCC." (PMID 26886558, 2016). "Univariate analysis showed that the significant prognostic factors for DFS in HCC patients were HBsAg, AFP, TNM stage, tumor number, portal vein tumor thrombus (PVTT), tumor differentiation, intraoperative blood loss, NLR, PLR, PNI and APRI (all P < 0.05)." (PMID 26907597, 2016). "As is known to all, the prognosis of HCC is related to the patient's age, gender, liver function, tumor metastasis, pathological changes, the level of AFP, the activity of immune cells, the number of platelets, and so on." (PMID 27462864, 2016). "With the progression of disease, the tumor widely metastasized and the serum AFP level increased progressively with the highest level of 3396 ng/mL." (PMID 27631210, 2016). "The HAP score consists of two measures of tumor burden (AFP and size of largest tumor) and two measures of liver function (albumin and bilirubin)." (PMID 27601241, 2016). "Univariate analysis showed that AFP, Edmondson–Steiner stage, tumor size, surgical margin, portal vein tumor thrombus (PVTT), vascular invasion, GPR, blood loss, and blood transfusion were all factors related to the OS in patients with HCC (all P < 0.05)." (PMID 27399101, 2016).
tumor (continued). "On univariate analyses, 5 variables significantly correlated with OS: tumor size, AFP, GGT, technique effectiveness and type of recurrence." (PMID 27620527, 2016). "On day 21 after tumor implantation, the AFP concentration in the vehicle group was 1,752,948 ± 1,338,693 ng/mL and that in the CBT-143-S-F6F7-treated group was 1,312,510 ± 944,306 ng/mL (P = 0.24)." (PMID 27502492, 2016). "In the correlation analysis, we observed that preoperative serum γ-GGT > 128 U/L exhibited a strong connection with AFP > 400 ng/ml, larger tumor, and macro and micro-vascular invasion." (PMID 27381639, 2016). "The association between the modules and HCC clinical traits (i.e., sex, age, tumor location, tumor grade and the AFP level) were identified." (PMID 27220887, 2016). "On multivariate analysis, 6 variables were significant prognosticators of OS: tumor number, tumor size, AFP, GGT and type of recurrence." (PMID 27620527, 2016). "This is a useful clinical marker for monitoring treatment effectiveness and tumor recurrence, since 90% of the patients at diagnosis have highly elevated serum levels of AFP." (PMID 26465815, 2016). "In multivariate analyses, higher AFP levels (>200 ng/mL; P = 0.010), larger tumor size (>2 cm; P = 0.012), Child–Pugh class B disease (P = 0.031), and higher ALT levels (>40 IU/L; P = 0.022) were independent predictors of OS." (PMID 27121318, 2016). "TMED3 up-regulation correlated with a high AFP level (P = 0.020), tumor size (P = 0.045) and vascular invasion (P < 0.001)." (PMID 27901021, 2016). "In contrast, AFP > 20 ng/ml and tumor location in more than one lobe were significant factor in patients outside the HKLC criteria (OR = 1.6, P = 0.048, OR = 1.6, P = 0.013, respectively)." (PMID 27323396, 2016). "Increased AFP levels (≥200 μg/L) were observed in 182 patients (56.7 %), and 95 patients (29.6 %) had multiple tumor masses." (PMID 26907597, 2016). "As described by other investigators, HCC tumor markers are AFP and protein induced by vitamin K absence or antagonist II,while ICC tumor markers are carcinoembryonic antigen (CEA) and carbohydrate antigen 19-9 (CA19-9)." (PMID 27835609, 2016). "Serum AFP levels were associated with LNM, vascular invasion, and liver metastasis, and serum CA125 was correlated with vascular invasion, LNM, and tumor stage." (PMID 27533455, 2016). "OS:Decline rates of the AFP level: favor TACE + PEI.Reduction rates of tumor size: favor TACE + PEI." (PMID 27167195, 2016). "In our case, the patient’s serum AFP level was markedly elevated to 12,310 ng/mL and the tumor cells in the liver were strongly and diffusely positive for AFP." (PMID 27301956, 2016). "The hazard of death was increased 1) with every cm increase in tumor size (HR=1.05, p = 0.017); 2) with every unit increase in AFP levels (HR=1.0004, p = 0.041); and 3) in subjects with BCLC stage C compared to BCLC stage B (HR=3.23, p < 0.001)." (PMID 26769845, 2016). "In the subgroups (tumor size, AFP level, tumor differentiation, TNM stage), HEY2 expression was reversely associated with the survival of post-resection HCC patients." (PMID 27191260, 2016). "Tumour markers have also been measured (alpha fetoprotein, beta human chorionic gonadotrophin and chorionic embryonic antigen, and all were within the normal range." (PMID 27173951, 2016). "Levels of AFP, tumor number, vascular invasion, satellite lesion, tumor encapsulation and Edmondson stage were also unfavorable prognostic variables for recurrence (all P values of <0.05)." (PMID 26928402, 2016). "Using two or more tumor markers AFP, protein induced by Vitamin K absence or antagonist-II (PIVKA-II), or AFP lectin fraction (AFP-L3) has been associated with increased sensitivity for detection of HCC." (PMID 27403337, 2016).
tumor (continued). "The other risk factors significantly associated with HCC recurrence were: advanced Edmondson grade at LR (P = 0.016), MVI at LR (P = 0.010), AFP level > 200 ng/mL at LT (P = 0.009), and advanced tumor node metastasis (TNM) staging at LT (P = 0.029)." (PMID 27145461, 2016). "Japanese retrospective study has also revealed that seven factors (distant metastases, portal invasion, intrahepatic tumor burden, serum AFP, DCP, albumin and total bilirubin) were independently related to a worse survival." (PMID 26931117, 2016). "We further compared diagnostic values of urinary molecules with classic blood tumor biomarkers CEA, CA19-9, CA72-4, CA12-5 and AFP on validating set." (PMID 27589838, 2016). "A full haematological screen should be performed including relevant tumor markers including beta hCG and alpha-fetoprotein." (PMID 26842759, 2016). "The Kaplan–Meier analysis suggested that AFP, tumor number, tumor size, capsule, microvascular invasion, differentiation, AJCC, and Milan criteria were associated with decreased actuarial DFS (all P < 0.05)." (PMID 27495049, 2016). "AFP is also a tumor marker and is secreted by several carcinomas and has therefore immunosuppressive activities." (PMID 28008329, 2016). "It was found that AFP is more sensitive for the diagnosis of small size tumours (<3 cm) while DCP is more sensitive for larger size tumours (>3 cm)." (PMID 26341083, 2015). "The most common methods used to diagnose HCC are radiographic imaging, liver biopsy and measurement of the serum tumor marker alpha-fetoprotein (AFP)." (PMID 25822740, 2015). "The majority of the HCC patients in the two cohorts were male (91.18%) with a tumor size of >5 cm at the time of surgery (45.96%), an elevated serum AFP level (47.79%) and with tumors exceeding the Milan and UCSF criteria (63.60 and 54.41%, respectively)." (PMID 25624916, 2015). "We identify the mannose receptor (MR/CD206) as the primary uptake pathway for both normal cord blood-derived AFP (nAFP) and tumor-derived AFP (tAFP) proteins." (PMID 26199728, 2015). "The corresponding sensitivity for AFP was 70.4 % and 40 % respectively indicating better sensitivity of AFP for small size tumours." (PMID 26341083, 2015). "Among these cases, the AFP-producing sites were identified by immunohistochemical examination of the resected tumor in 7 cases only (including the current case)." (PMID 25886790, 2015). "Tumor markers: alpha-fetoprotein (AFP), CA 19-9 (carcinogenic antigen 19-9) and carcinogenic embryonic antigen (CEA) within normal limits advocate for the benign nature of the lesion." (PMID 26361504, 2015). "At present, tumor grade, tumor size, microscopic/macroscopic vascular invasion, and the alpha fetoprotein levels are considered to be important predictors of tumor recurrence." (PMID 26160837, 2015). "We demonstrated that ATAD2 was over-expressed in HCC patients, where high ATAD2 levels were significantly correlated with aggressive phenotypes such as high AFP levels, advanced tumor stages, and vascular invasion." (PMID 26497681, 2015). "Close follow-up with serial AFP level monitoring should be done for 5 years after initial tumor resection and coccygectomy." (PMID 26504900, 2015). "We further investigated the predictive value of PKM2 expression within patient subgroups and found that the prognostic significance of PKM2 retained within the Edmondson I-II, Edmondson III-IV, single tumor, AFP ≤ 20 ng/mL, and TNM stage I subgroups." (PMID 25514599, 2015). "The clinico-pathological characteristics of this tumor were evaluated, and the literature about AFP-producing pNETs was reviewed." (PMID 25886790, 2015). "Although local resection was performed 2 months before the diagnosis of AFP tumor, the serum AFP levels of 2 months after the initial operation were normal." (PMID 25962419, 2015).